CDKL3 (cyclin dependent kinase like 3)
Synonyms: NKIAMRE
Tractability: Small molecule: a structure with a bound ligand is known; a high-quality ligand is known; it belongs to a druggable protein family. PROTAC: a small molecule that binds it is known.
Target class: Protein Kinase; CMGC protein kinase CDKL family; CMGC protein kinase group; Enzyme; Kinase
Gene: Protein-coding gene on chromosome 5 (134,286,350 to 134,371,047, reverse strand). Ensembl gene ENSG00000006837.
Subcellular location: Cytoplasm
Subcellular location (Human Protein Atlas): Nucleoplasm; Vesicles
Gene Ontology:
Molecular function: protein binding; protein kinase activity; ATP binding; cyclin-dependent protein serine/threonine kinase activity; protein serine kinase activity
Biological process: dendrite extension; negative regulation of axon extension; positive regulation of dendrite morphogenesis; protein modification process; regulation of cell cycle
Cellular component: cytoplasm
Genetic constraint (gnomAD): Loss-of-function variants: 32 observed, 28.22 expected, observed/expected ratio (o/e) 1.13, 90% interval 0.86 to 1.52. The upper end of that interval is the gene's LOEUF score, 1.52, which puts it in group 6 of 6, group 1 being the genes least tolerant of losing a copy. Missense variants: 388 observed, 401.49 expected, observed/expected ratio (o/e) 0.97, 90% interval 0.89 to 1.05. Synonymous variants: 120 observed, 134.26 expected, observed/expected ratio (o/e) 0.89, 90% interval 0.77 to 1.04.
Homologues: Orthologues: chimpanzee CDKL3 (99% identical), dog CDKL3 (87% identical), pig CDKL3 (81% identical), mouse Cdkl3 (81% identical), rabbit CDKL3 (81% identical), rat Cdkl3 (79% identical). Paralogues in human: CDKL2 (39% identical), CDKL5 (29% identical), CDKL1 (27% identical), CDKL4 (26% identical), CDK12 (20% identical), CDK13 (20% identical), CDK8 (19% identical), CDK1 (19% identical), CDK11A (19% identical), CDK11B (19% identical), CDK19 (19% identical), CDK17 (18% identical), and 14 more.
Diseases named in the same sentence as CDKL3 in open-access papers:
CDKL3 is named in the same sentence as 22 diseases in open-access papers, as found by Europe PMC text mining. Sharing a sentence is not in itself a finding about the gene and the disease. The quoted sentences say what the papers report.
cholangiocarcinoma (4 papers, 2018 to 2024). A carcinoma that arises from the intrahepatic biliary tree (intrahepatic cholangiocarcinoma) or from the junction, or adjacent to the junction, of the right and left hepatic ducts (hilar cholangiocarcinoma). "Recent studies have found abnormal expression of CDKL3 in several cancers, particularly osteosarcoma, esophageal squamous cell carcinoma, colorectal cancer, glioma, and cholangiocarcinoma." (PMID 38993199, 2024). "By reducing the expression of the target gene CDKL3 and arresting the cell cycle in the G1 phase, CC inhibits proliferation and promotes apoptosis in cholangiocarcinoma HCCC-9810 and RBE cells." (PMID 35911648, 2022). "In our current research, we tested the effect of curcumol in cholangiocarcinoma cells, and using two-dimensional electrophoresis, proteomics and bioinformatics, we identified cyclin-dependent kinase like 3 (CDKL3) as a potential target for curcumol." (PMID 29615928, 2018). "Recent studies have investigated the oncogenic role of CDKL3 in various tumors, including glioma, oesophageal squamous cell carcinoma, osteosarcoma, colorectal cancer, breast cancer, and cholangiocarcinoma." (PMID 38993199, 2024). "Given the high level of CDKL3 expression in human cholangiocarcinoma tissues and cell lines, we speculated that CDKL3 may constitute a potential biological target for curcumol in cholangiocarcinoma." (PMID 29615928, 2018). "Moreover, CDKL3 was considered as a therapeutic target of curcumol, a major component extracted from the root of Rhizoma Curcumae, mediating the anticancer effects in cholangiocarcinoma cells." (PMID 36899018, 2023).
esophageal squamous cell carcinoma (4 papers, 2020 to 2024). Esophageal squamous cell carcinoma (ESCC) is a type of esophageal carcinoma (EC) that can affect any part of the esophagus, but is usually located in the upper or middle third. "Our previous study suggested cyclin-dependent kinase-like 3 (CDKL3) acts as a new oncogene in esophageal squamous cell carcinoma (ESCC) cell line TE-1." (PMID 32974198, 2020). "The relationship between CDKL3 expression and postoperative pathological complete response (pCR) rate in esophageal squamous cell carcinoma (ESCC) patients undergoing neoadjuvant chemoradiotherapy (nCRT) was evaluated using Immunohistochemical staining (IHC)." (PMID 38562942, 2024). "Our previous study identified CDKL3 as an important oncogene in esophageal squamous cell carcinoma (ESCC) and autophagy-related gene ATG5 was a potential target of CDKL3 in KYSE-150 cell line." (PMID 38562942, 2024).
osteosarcoma (4 papers, 2020 to 2024). A usually aggressive malignant bone-forming mesenchymal neoplasm, predominantly affecting adolescents and young adults. "In osteosarcoma, CDKL3 was also found to be capable of affecting autophagy by activating Akt signaling pathway, as well as other downstream effects of Akt pathway such as cell growth and cell apoptosis." (PMID 36899018, 2023). "Article: He A, Ma L, Huang Y, Zhang H, Duan W, Li Z, Fei T, Yuan J, Wu H, Liu L, Bai Y, Dai W, Wang Y, Li H, Sun Y, Wang Y, Wang C, Yuan T, Yang Q, Tian S, Dong M, Sheng R, Xiang D (2020 Mar 31) CDKL3 promotes osteosarcoma progression by activating Akt/PKB." (PMID 36270774, 2022).
prostate carcinoma (3 papers, 2023 to 2024). A carcinoma that arises from epithelial cells of the prostate gland. "Subsequent cellular phenotyping assays showed the role of STAT1 in prostate cancer progression and its association with CDKL3." (PMID 36899018, 2023). "In summary, in vitro loss-of-function experiments clearly point to the fact that CDKL3 may have an important role in the disease progression of prostate cancer." (PMID 36899018, 2023). "The most recent study unveiled a substantial upregulation of CDKL3 expression in prostate cancer tissues, which is positively correlated with the degree of tumor malignancy." (PMID 39130630, 2024). "Recent studies suggested that upregulated CDKL3 expression is critical for promoting tumor development and poor prognosis in various solid tumors, including glioma and prostate cancer." (PMID 38562942, 2024). "Herein, the outcomes of in vitro and in vivo studies suggested similar regulatory functions of CDKL3 in prostate cancer as that in other types of human cancers." (PMID 36899018, 2023). "Prostate cancer cells with CDKL3 knockdown exhibited weakened proliferative activity, enhanced apoptosis, and decreased motility, while xenografts formed by CDKL3 knockdown cells showed distinctly slower growth rates than that formed by control cells." (PMID 36899018, 2023). "The association between CDKL3 and tumor progression was clearly indicated by the CDKL3 upregulation in prostate cancer tissues and its correlation with Gleason score and tumor stage, both of which are important characteristics of prostate cancer." (PMID 36899018, 2023). "As the beginning of this study, we preliminarily investigated the role of CDKL3 in prostate cancer progression by analyzing its expression in 156 prostate cancer tumor tissues and 32 adjacent normal tissues." (PMID 36899018, 2023). "In this study, we investigate the expression pattern and biological functions of CDKL3 in prostate cancer on clinical, cellular, and animal levels." (PMID 36899018, 2023). "The outcomes of this work showed that CDKL3 was significantly upregulated in prostate cancer tissues compared with adjacent normal tissues, and was significantly positively correlated with tumor malignancy." (PMID 36899018, 2023). "In summary, this work identifies CDKL3 as a new prostate cancer-promoting factor, which also has the potential to be a therapeutic target for prostate cancer." (PMID 36899018, 2023). "Knockdown of CDKL3 levels in prostate cancer cells significantly inhibited cell growth and migration and enhanced apoptosis and G2 arrest of the cell cycle." (PMID 36899018, 2023). "Functionally, STAT1 is aberrantly overexpressed in prostate cancer and has a tumor-promoting effect similar to that of CDKL3." (PMID 36899018, 2023). "In this study, as far as we know, the participation of CDKL3 in the development of prostate cancer was investigated for the first time." (PMID 36899018, 2023). "More importantly, the phenotypic changes of prostate cancer cells induced by CDKL3 were dependent on ERK pathway and STAT1." (PMID 36899018, 2023). "Furthermore, CDKL3 has emerged as a novel promoter of prostate cancer and holds the potential as a therapeutic target for this disease, providing new ways of treatment development." (PMID 39130630, 2024). "Although a small number of studies have demonstrated the aberrant expression and progression regulation ability of CDKL3 in malignant tumors, its function and mechanism in prostate cancer remain unclear." (PMID 36899018, 2023). "All these results suggested a key role of CDKL3 in the development of prostate cancer." (PMID 36899018, 2023). "CDKL3 is a molecule with a recently discovered regulatory role in human tumors, and its relationship with prostate cancer is unknown." (PMID 36899018, 2023).
prostate carcinoma (continued). "Knockdown of STAT1 could not only inhibit prostate cancer development in vitro, but also diminish the promotion effects induced by CDKL3 overexpression, highlighting the critical role of STAT1 as the mediator." (PMID 36899018, 2023). "Moreover, a potential downstream mediator, STAT1, was identified by a preliminary mechanistic study, whose essential role in CDKL3-induced prostate cancer regulation was subsequently proved." (PMID 36899018, 2023). "Validation experiments showed that both CDKL3 knockdown lentivirus (shCDKL3) as well as control lentivirus (shCtrl) could efficiently infect prostate cancer cells and knockdown the mRNA as well as protein levels of CDKL3." (PMID 36899018, 2023). "Therefore, we can conclude that CDKL3 may promote the progression of prostate cancer through STAT1." (PMID 36899018, 2023). "In conclusion, CDKL3 was identified to possess a STAT1-dependent tumor-promoting factor in the development and progression of prostate cancer, which could contribute to the improvement of targeted therapy for prostate cancer." (PMID 36899018, 2023).
anaplastic large cell lymphoma (2 papers, 2006 to 2018). Anaplastic large cell lymphoma (ALCL) is a rare and aggressive peripheral T-cell non-Hodgkin lymphoma, belonging to the group of CD30-positive lymphoproliferative disorders, which affects lymph nodes and extranodal sites. "In this perspective, high expression of CDKL3 was detected in two aggressive types of anaplastic large cell lymphoma (ALCL) tumors when compared to peripheral blood lymphocytes." (PMID 29615928, 2018).
glioma (2 papers, 2024). A benign or malignant brain and spinal cord tumor that arises from glial cells (astrocytes, oligodendrocytes, ependymal cells). "Upregulation of CDKL3 expression in glioma tissue independently predicts poor patient prognosis." (PMID 38562942, 2024).
hepatocellular carcinoma (2 papers, 2023 to 2024). A malignant tumor that arises from hepatocytes. "BM-MSC-EXOs miR-205–5p exerts inhibitory efficacy on developing hepatocellular carcinoma (HCC) via controlling CDKL3." (PMID 36690996, 2023).
colon cancer (1 paper, 2024). "In particular, CDKL3 has significant clinical relevance in colon cancer, and the effectiveness of HZ1 was demonstrated by murine and patient-derived cancer models." (PMID 38963708, 2024). "The transcriptome databases showed that CDKL3 was much more highly expressed in colon cancer tissue than in normal adjacent tissues." (PMID 38963708, 2024). "Collectively, we have established a robust clinical connection between CDKL3 and colon cancer overall." (PMID 38963708, 2024). "Both CDK4 and pRb positively correlated with CDKL3 in the colon cancer tissues." (PMID 38963708, 2024). "A CDKL3 inhibitor such as HZ1 could efficiently clear the tumor burden derived from the colon cancer patient." (PMID 38963708, 2024). "Additionally, a strong correlation existed between a high level of CDKL3 and poor prognosis for patients with colon cancer." (PMID 38963708, 2024). "All these clues together suggested that CDKL3 was not favored in colon cancer." (PMID 38963708, 2024).
developmental disabilities (1 paper, 2020). "Patients with mutations in CDKL2, CDKL3 or CDKL5 exhibit symptoms in intellectual and developmental disabilities." (PMID 32134924, 2020).
esophageal adenocarcinoma (1 paper, 2024). A malignant tumor with glandular differentiation arising predominantly from Barrett mucosa in the lower third of the esophagus. "It is necessary to further distinguish the role of CDKL3 in ESCC patients from esophageal adenocarcinoma patients." (PMID 38562942, 2024). "Although bioinformatics analysis was conducted in ESCA patients including ESCC and esophageal adenocarcinoma, the vitro study evidence only confirmed the role of CDKL3 in ESCC cell lines while lacking data in esophageal adenocarcinoma." (PMID 38562942, 2024).
esophageal cancer (1 paper, 2024). A primary or metastatic malignant neoplasm involving the esophagus. "However, the potential role of CDKL3 in immunotherapy and the tumor microenvironment (TME) in esophageal carcinoma (ESCA) remains unclear." (PMID 38562942, 2024).
fatty liver disease (1 paper, 2024). A reversible condition wherein large vacuoles of triglyceride fat accumulate in liver cells via the process of steatosis. "In a separate study, we have generated Cdkl3-floxed mice and discovered the important role of Cdkl3 in fatty liver diseases." (PMID 38963708, 2024).
melanoma (1 paper, 2024). A malignant, usually aggressive tumor composed of atypical, neoplastic melanocytes. "We discovered that the prognosis, including OS and progression-free survival (PFS), was worse for the high CDKL3 group in the metastatic urothelial cancer and melanoma cohorts (p < 0.05)." (PMID 38562942, 2024).
Stroke (1 paper, 2025). Sudden impairment of blood flow to a part of the brain due to occlusion or rupture of an artery to the brain. "Upregulation of ADGRL1, CDK5R1/CDKL3, CHRNB2, and ROR2 genes in post-stroke long-lasting brain fatigue generally supports neuroplasticity, cognitive recovery, and neurogenesis, which are beneficial for rehabilitation." (PMID 40006074, 2025). "The upregulation of ADGRL1, CDK5R1/CDKL3, CHRNB2, and ROR2 gene expression in the context of long-lasting post-stroke brain fatigue can have a mix of positive and negative effects, depending on how these proteins influence brain function, recovery, and energy regulation." (PMID 40006074, 2025).
tumor (9 papers, 2018 to 2024). "CDKL3 was strongly related to 25 immune-related signatures in the TCGA cohort, most of which were anti-tumor signatures that were negatively associated with CDKL3." (PMID 38562942, 2024). "The high expressions of CDKL3 were positively associated with the tumor-node-metastasis (TNM) stage and Ki67." (PMID 32974198, 2020). "This provided a different perspective on the mechanism by which high CDKL3 expression leads to attenuated anti-tumor immunity." (PMID 38562942, 2024). "Compared to the paired normal tissue samples in GEO databases, CDKL3 was highly overexpressed in the tumor tissues of ESCA (GSE161533 and GSE23400." (PMID 38562942, 2024). "An analysis of immunotherapy cohorts of the ESCA and pan-cancer showed a better response to immunotherapy in tumor patients with lower CDKL3 levels." (PMID 38562942, 2024). "Spearman analysis indicated that CDKL3 expression was significantly and negatively related to the majority of tumor-infiltrating immune cells (TIICs)." (PMID 38562942, 2024). "In the TCGA cohort, CDKL3 expression was negatively correlated with the activity of step 4 of the cancer immunity cycles, i.e. immune cell trafficking to the tumor, which was further validated in the GSE47404 cohort." (PMID 38562942, 2024). "The potential function of CDKL3 in the modulation of tumor microenvironment and autophagy has been initially identified in this study, but a further prospective exploration needs to be designed to confirm." (PMID 38562942, 2024). "Existing research demonstrates that tumor patients with CDKL3 up-regulation are closely related to inferior survival status." (PMID 38562942, 2024). "This acts as a tumor suppressor by decreasing cell proliferation, invasion, and metastasis by regulating the expression of cyclin-dependent kinase-like 3 (CDKL3)." (PMID 37237523, 2023). "They showed that CDKL3 exerts tumor-promotor-like functions in the development of ESCC, with upregulated expression in tumor tissues, a significant correlation with poor prognosis of patients, a distinct regulatory ability of malignant cell phenotypes." (PMID 36899018, 2023). "By further including tumor pathological indicators in statistical analysis, the results showed that upregulated CDKL3 expression was positively correlated with the malignancy of the tumor (tumor stage as well as Gleason score)." (PMID 36899018, 2023). "Tumors generated from U2OS cells with CDKL3 knockdown was ∼2-fold smaller than that of the control group, along with the significant difference of tumor weight between them (0.180 ± 0.008g versus 0.361 ± 0.033g, ***P < 0.001)." (PMID 32234750, 2020). "Then, UALCAN and TCGA datasets were employed to analyze the expression profile of these potential target genes of CDKL3 based on tumor histology." (PMID 32974198, 2020). "A transplanted tumor model was established to study the functions of CDKL3 on the tumorigenesis of ESCC cells." (PMID 32974198, 2020). "CDKL3 emerged as a positive regulator of Akt signaling pathway, autophagy inactivation, and programs that correlate to tumor progression." (PMID 32234750, 2020). "ESCC tumor tissues possessed a significantly higher expression of CDKL3 and autophagy-related gene 5 (ATG5) than matched adjacent normal tissues." (PMID 32974198, 2020). "Our results from 46 paired tumor and normal adjacent tissues indicated that CDKL3 and ATG5 were, respectively, high-expressed in 32 of 46 (69.56%) and 41 of 46 (89.13%) cases of ESCC, which was statistically higher than that in the adjacent non-tumor tissue." (PMID 32974198, 2020). "Notably, CDKL3 was also closely correlated with tumor immune cell infiltration and the expression of immune checkpoint markers." (PMID 38993199, 2024). "The observed tumor-inhibiting effect resulting from reduced CDKL3 expression indicates that CDKL3 may also be a promising molecular target for HCC therapy." (PMID 38993199, 2024).